RNU6-426P (RNA, U6 small nuclear 426, pseudogene)
Gene: Small nuclear RNA gene on chromosome 21 (16,035,413 to 16,035,509, reverse strand). Ensembl gene ENSG00000252273.
Homologues: Orthologues: chimpanzee U6 (100% identical), rat LOC120102605 (69% identical), guinea pig U6 (66% identical), mouse Gm54599 (64% identical), rabbit U6 (62% identical), dog U6 (59% identical). Paralogues in human: RNU6-1209P (78% identical), RNU6-838P (78% identical), RNU6-500P (77% identical), RNU6-533P (77% identical), RNU6-59P (77% identical), RNU6-742P (77% identical), RNU6-1145P (76% identical), RNU6-151P (76% identical), RNU6-254P (76% identical), RNU6-38P (76% identical), RNU6-393P (76% identical), RNU6-1005P (75% identical), and 1288 more.